CD22 (CD22 molecule)
Diseases named in the same sentence as CD22 in open-access papers (continued):
Sharing a sentence is not in itself a finding about the gene and the disease.
tumor (continued). "Then Chidamide was given by gavage at a final concentration of 3 mg/kg on day 10, and then the apoptosis and the site density of CD22 on the surface of tumor cells in peripheral blood were measured by orbital blood collection intermittently after successive 3 days of gavage." (PMID 34667217, 2021). "Moreover, the sensitivity of CD22-positive tumor cells was correlated with CD22 expression on the cells’ surface." (PMID 34976821, 2021). "In a model recapitulating the loss of CD19 (CD19−/CD22+ tumor), AUTO3 CAR T cells were able to stop tumor growth and reduce tumor burden and had a higher CAR T cell persistence in the bone marrow compared with the FMC63 CAR, which showed no improvement over non-transduced T cells." (PMID 34642489, 2021). "Using this assay, we sought to determine whether synthetic bryostatin 1 and bryostatin analogs could achieve sufficient increase in CD22 surface density as required for CD22-targeted CAR T cell-mediated tumor clearance." (PMID 32312992, 2020). "Consequently, antibody (or sialoside-based) immunotoxins can be used to target the tumor cell using CD22 as a means of entry." (PMID 32012891, 2020). "Interestingly, the cell markers that differed in cell culture conditions were somewhat different than those detected in tumor cells; CD22 and CD138 were more commonly expressed in ΔvIL-6 cells in culture but not in tumor cells." (PMID 30265712, 2018). "DOX accumulation at tumor sites in the DOX–platelet–CD22 group was the highest." (PMID 28938559, 2017). "Therefore, DOX–platelet–CD22 targets tumor sites and decreases the dosage of cytotoxic drugs necessary for chemotherapeutic activity." (PMID 28938559, 2017). "Anti-CD22 mAb-labeled platelets can precisely deliver DOX to tumor cells." (PMID 28938559, 2017). "A tumor-bearing mouse model was established to estimate the in vivo effects of DOX–platelet–CD22." (PMID 28938559, 2017). "The in vitro anti-tumor effects of DOX–platelet–CD22 were subsequently evaluated." (PMID 28938559, 2017). "Platelets and anti-CD22 mAbs can increase DOX accumulation in tumor cells." (PMID 28938559, 2017). "In the present study, we generated a recombinant anti-CD22 scFv–apoptin fusion protein as a bifunctional molecule: the anti-CD22 scFv moiety targets the CD22 antigen on malignant B-cells surface and apoptin specifically kills the tumor cells." (PMID 28582973, 2017). "Moreover, DOX–platelet–CD22 showed platelet properties, such as tumor cell-induced platelet aggregation." (PMID 28938559, 2017). "Moreover, tumour cells exhibited reduced surface expression of CD22 and of PD-1, and diminished SHP-2 phosphatase activity in comparison to WT cells." (PMID 27297662, 2016). "CD22 is a member of the Sialic acid-binding Ig-like lectin (Siglec) family of lectins described to be exclusively present in B lymphocytes and B cell-derived neoplasms." (PMID 25957418, 2015). "One patient with end-stage NHL received a total of 5 mg of saporin-S6 complexed with a pair (50 mg) of anti-CD22 bispecific Abs over 15 days (0, +7, +15), achieving a complete clearance of the tumor from the blood, clearance of the ascites and shrinkage of the tumor masses." (PMID 24105401, 2013). "The tumor cells were only weakly positive for CD22 and CD30, but strongly positive for CD4." (PMID 23880011, 2013). "However, despite the description of some durable complete tumour responses, the advantage of adding the humanised anti-CD22, epratuzumab to the standard treatment with anti-CD20 rituximab, has not yet been convincingly demonstrated." (PMID 21504579, 2011). "Moreover, we found that IBC tumour-infiltrating B cells also presented high levels of immature signals, which was reflected mainly in the significantly high expression of five molecules, CD22, FCRL1, FCRLA, HVCN1, and SP100, in IBC tumour-infiltrating B cells." (PMID 40624675, 2025).
tumor (continued). "Additionally, the role of CD22 in immune suppression and its selective expression on B cells makes it an attractive target for selective therapies that aim to minimize off-target effects and maximize the immune response against the tumor cells." (PMID 38881902, 2024). "Here, we present a patient who had suffered from several recurrences previously and controlled well with a very small tumor lesion left was infused with CD19/CD22 bispecific CAR-T, with no immune effector cell-associated neurotoxicity syndrome, or cytokine release syndrome observed." (PMID 38090479, 2023). "These different tumor types may have different binding receptors and CD22 antigen expression." (PMID 30859374, 2019). "Moreover, tumor size was the smallest in the DOX–platelet–CD22 group." (PMID 28938559, 2017). "Therefore, these cell subsets could be affected by on-target off-tumor toxicity of CD22-specific mAbs or CAR-engineered T-cells." (PMID 27689397, 2016). "In addition, IHC staining of tumor biopsies confirmed the expression of CD22 in CD4+ T cells." (PMID 25957418, 2015). "For example, CD22 (SIGLEC2) is expressed on B cells and binds to the tumor prognosis marker Neu5AC-α2–6-GalNAc." (PMID 40076391, 2025). "B-ALL is a neoplasm of precursor lymphoid cells committed to the B-cell lineage, characterized by the expression of CD19, CD22, cytoplasmic CD79a, and/or PAX5, as determined by flow cytometry or immunohistochemistry." (PMID 41333696, 2025). "Diagnosis is primarily cytological, hinging on the classic “starry sky” appearance, alongside immunophenotyping that shows tumor cells positive for B‐cell markers (CD19, CD20, CD22, CD79a, CD38, PAX5) and germinal‐center markers (CD10, BCL6)." (PMID 40951226, 2025). "Further experiments on tumor (Raji, Mino, Jurkat) and normal immune cells (PBMC) showed that DOX–platelet–CD22 had a more pronounced cytotoxic effect on tumor cells and a reduced effect on PBMC." (PMID 40943069, 2025). "Therefore, although the CD25+/CD22+weak association has been described as a phenotypic feature of the WM tumour cell, it could not be assessed in this study." (PMID 40407640, 2025). "In mouse models, MT-SLP-76 rescues the activity of CD22-, CD19- and B cell maturation antigen (BCMA)-targeting CARs against antigen-low tumor cells." (PMID 41131392, 2025). "The FUS IDR consistently promoted antitumor effects in all three tumor models (CD19, HER2 and CD22)." (PMID 41023404, 2025). "Several immune-related genes were shared across tumor types, with seven genes (CASP3, F2RL1, CD22, RORC, PLA2G6, SYCP1, MAP3K5) common to all four histologies." (PMID 40621458, 2025). "Expanding upon this strategy, PET probes similar to the CD19 probe developed here can be developed for additional CARs targeting distinct protein tumor antigens, such as BCMA, CD22, and HER2." (PMID 39292778, 2024). "We used a concentration of 350 nM Rituximab to treat tumor cells, followed by flow cytometry to detect the expression of CD19 and CD22." (PMID 38662336, 2024). "Autologous CAR T cells have shown robust anti-tumor activity against hematological malignancies targeting BCMA, CD20, CD22, and CD30." (PMID 38637886, 2024). "Firstly, we evaluated the tumor killing effect by selecting CD19, CD20, and CD22 simultaneously antigen-expressing B-ALL cells (NALM-6) as well as primary cells." (PMID 38662336, 2024). "CART cells are engineered to specifically recognize target tumor antigens, such as CD19, CD20, and CD22, in B ALL, and to rapidly activated to kill tumor cells." (PMID 39273126, 2024). "For successful effector functions, it is imperative for CAR T cells to rapidly recognize tumor cells and facilitate CAR receptor binding with the CAR antigen (e.g., CD19, CD20, CD22, BCMA, etc.)expressed on tumor cells." (PMID 38558801, 2024). "To investigate the effects of Rituximab on the expression of surface marker molecules on CD19/CD22 CAR-T cells, we co-cultured Rituximab-treated tumor cells with CAR-T cells for 24 h." (PMID 38662336, 2024).
tumor (continued). "We further found that a combination of αCD3xαCD22 and blinatumomab exhibits an enhanced anti-tumor effect in our mouse model, warranting further investigation of dually targeting CD19/CD22 through T-cell engaging treatment modalities." (PMID 37247022, 2023). "The most important tumor antigens targeted by NbCAR-T cells against B cell malignancies include CD19, CD22, CD20, CD33, and CD72." (PMID 36761751, 2023). "We explored the differential expression of the SIGLEC family in tumor and normal tissue in GEPIA and found that the content of CD22, SIGLEC7, and SIGLEC9 in the tumor was higher than that in normal tissue." (PMID 37207210, 2023). "The combination of C2 and additional therapeutic mAbs, such as type II anti-CD20/CD22/CD38 samples, can overcome complement attack resistance in tumor cells." (PMID 37071001, 2023). "Based on this, we constructed CD22 CAR-NK cells, then testing their ability to kill tumor cells in vitro." (PMID 37817249, 2023). "Ten signaling pathways only existed in the lymphatic metastases, including CD22, CD45, IL16, SPP1, LIGHT, ANGPTL, GRN, ncWNT, PERIOSTIN, and NEGR, in addition to the classical ncWNT pathways that can promote tumor progression." (PMID 37221625, 2023). "According to the WHO definition, CLL/SLL cells typically co-express CD5 and CD23, and flow cytometry reveals that tumor cells express dim surface IgM/IgD, CD20, CD22, CD5, CD19, CD79a, CD23, CD43, and CD11c (weak)." (PMID 38258066, 2023). "Dual targeting CD22/CD19- and CD20/CD19-CAR-T cell products showed significant activity against R/R B-NHLs, emerging as a promising strategy to overcome tumor antigen escape mechanisms." (PMID 38201473, 2023). "On-target, off-tumor effect of anti-CD19 and anti-CD22 CAR-T cells on normal B-cells generates B-cell aplasia and subsequent hypogammaglobulinemia." (PMID 38003910, 2023). "A trispecific NbCAR-T (triNbCAR-T), LCAR-AIO, simultaneously targets three different tumor antigens, including CD19, CD20, and CD22, to treat patients with recurrent B cell malignancies." (PMID 36761751, 2023). "The generated CAR-macrophages specifically recognized the cognate CD19, CD22 or HER2 antigens, phagocytosed antigen-bearing tumor cells, cross-presented tumor antigens, provided T-cell costimulation and inhibited tumor growth in vitro." (PMID 35725499, 2022). "Multiple B-cell subpopulation markers are unevenly expressed in B cells, such as CD22, CD27, and CD38, suggesting B-cell heterogeneity in the tumor microenvironment." (PMID 35634306, 2022). "By targeting those two tumor-expressed receptors, the bi-specific immunotherapeutic agent resulted in a better outcome for DLBCL patients who expressed CD19 and CD22 heterogeneously than CAR T cells that targeted CD19 only." (PMID 34514097, 2021). "Since, we saw development of humanized antibodies, next generations anti-CD20, mAbs targeting other markers on tumor cells (CD19 and CD22), its microenvironment (PD-1, CD47), antibody drug conjugates and bispecific T cell engagers." (PMID 34765437, 2021). "First, second and third generation CAR NK cells have been generated, using lentiviral vectors, to target tumor antigens such as CD19, CD20, CD33, CD7, CD22, ErbB2 and EGFR." (PMID 33450862, 2021). "In order to confirm that the Sepax spinoculation did not affect the functional properties of the CAR T-cells, a killing assay was set up using NALM6 tumor cells, which expresses both CD19 and CD22 targets along with GFP that was used to quantitate the cells." (PMID 34819105, 2021). "For that purpose, CD22(+) and CD22(−) RAJI tumor cells expressing firefly luciferase were transplanted subcutaneously into the left and right flanks of NSG mice, respectively." (PMID 31723132, 2019). "Efforts to overcome primary or secondary resistance thus include multi or tandem CAR T cells targeting two different tumor antigens (e. g., CD19 and CD22), or the use of checkpoint inhibitors or interleukin-15 to reactivate exhausted CAR T cells." (PMID 29983827, 2018).
tumor (continued). "Intracellular DOX concentration significantly increased in CD22+ tumor cells (Raji and Mino cells) that were treated with DOX–platelet–CD22 compared with those in cells treated with DOX alone or DOX–platelet." (PMID 28938559, 2017). "We found that direct contact between Raji tumor cells and CAR T cells was necessary to down-modulate Raji surface expression of CD19, CD20 and CD22." (PMID 28515942, 2017). "In previous studies, we demonstrated that the anti-tumor efficacy of both the anti-CD20 mAb rituximab and the anti-CD22 mAb OM124 can be strongly augmented by their conjugation to RIPs." (PMID 28556822, 2017). "By contrast, the average tumor size of mice that were treated with DOX alone, DOX–platelet, or DOX–platelet–CD22 steadily decreased." (PMID 28938559, 2017). "The tumor volumes of DOX, DOX–platelet, and DOX–platelet–CD22 mice significantly decreased compared with those of the controls." (PMID 28938559, 2017). "Altogether, our data indicate that anti-CD22 mAbs and platelets facilitate DOX accumulation in tumor cells, which inhibits tumor growth by blocking cell cycle progression, suppressing proliferation, and inducing apoptosis." (PMID 28938559, 2017). "All tumor populations demonstrated full recovery, with CD19, CD20, and CD22 expression being greater than 98%." (PMID 28515942, 2017). "Additionally, 211At-labeled anti-CD22 RIT has emerged as a promising alternative for B-cell malignancies, benefiting from the short-range, high-energy α-particle emissions, which enhance tumor cell killing while minimizing off-target toxicity." (PMID 40227793, 2025). "Additionally, 212Pb, a β-to-α generator, is being explored for its potential in treating NHL, especially with its ability to target CD22- and CD37-expressing tumor cells." (PMID 40227793, 2025). "Tumor cells were positive for CD38, CD138, CD22, CD79a, MUM1, CD45, and kappa; partial positive for CD19 and EBER; negative for CD2, CD3, CD5, CD10, CD20, CD56, cyclin D1, ALKp80, HHV-8, MPO, lambda and IgG; and 5% positive for CD30; the Ki-67 positivity rate was 70%." (PMID 41235228, 2025). "Indeed, MCLs express the neoplasm markers of mature B cells, namely CD19, CD20, CD22, CD79-A, and Cyclin D1." (PMID 38828423, 2024). "T cells expressing Bi-ChTCRs targeting CD19 and CD22 or BCMA and SLAMF7 recognized target cells expressing either one or both target proteins and exhibited superior sensitivity for tumor cells with low antigen levels compared to T cells expressing monospecific and bispecific CARs." (PMID 38746248, 2024). "And in the ligand-receptor interaction, the B cells activation group exhibited more CSF, CXCL, and MHC-I signaling pathway, while CD22, and CD23 was inhibited, indicating that the B cells activation group improved anti-tumor immunity through cell-cell intercommunication." (PMID 38622125, 2024). "CAR-M targeting CD19, CD22, HER-2, CD5, and carcinoembryonic antigen-related cell adhesion molecule 5 (CEACAM5) have been developed to fight against solid tumors and hematopoietic malignancies with improved tumor control and significant activation of TME." (PMID 38195534, 2024). "In our patient samples, IHC staining showed that CD22 was expressed in 80.46% (70/87) of patients, whereas 19.54% (17/87) samples had little or no expression of CD22 in the tumor cells." (PMID 37817249, 2023). "One patient showed a transient response to CD19 CAR-T cell therapy, probably due to CD19 CAR-T cells not expanding adequately, so he received CD22 CAR-T cell therapy as soon as the tumor regrowth was detected." (PMID 38003910, 2023). "However, our study is limited by the variability in tumor reduction chemotherapy regimens, the small sample size and short follow-up duration of the sequential CD19/CD22 CAR T-cell group, and the difference in CAR T-cell infusion doses among the three groups." (PMID 37095120, 2023). "All of CD22‐positive tumor cell lines but not CD22‐negative cells efficiently responded to CD22 CAR‐T cells." (PMID 35665369, 2022).
tumor (continued). "Both CD37 and CD22 are expressed across most NHL forms and rapidly internalized after Ab binding, further improving the retention of the conjugated radioisotope within the tumor site." (PMID 35865548, 2022). "Indeed, pre-clinical studies have shown anti-tumor activity of TTCs as monotherapy across a broad range of tumor types, and TTCs targeting HER2, PSMA, MSLN, and CD22 are under investigation in clinical studies." (PMID 36726355, 2022). "The cytotoxicity ability of CD22 CAR‐T cells depends on the E/T ratio increase but not the expression level of CD22 on the surface of target tumor cells." (PMID 35665369, 2022). "We observed that PD‐L1 expressed by CD22 CAR‐T cells is irrespective of PD‐L1 expression in target tumor cells." (PMID 35665369, 2022). "An example is CD22-specific AAV-Cpf1 KIKO CAR-T, a CAR-T product with homology-directed repair knockin and immune checkpoint knockout, which has exhibited lower-level exhaustion markers but comparable tumor control effect with regard to Cas9 CAR-T." (PMID 33921581, 2021). "Additionally, CD22 (chromosome 19) was evidenced in more than half of the PDS cohort and one AFX tumor." (PMID 34202213, 2021). "Spontaneous DLBCL in dogs is a tumor model that may help accelerate the development of new methodologies and therapeutic strategies for RIT targeting CD22." (PMID 32117707, 2020). "Therefore, CD16-directed bispecific (eg, CD16 and CD19) or trispecific (eg, CD16 and two tumor antigens CD19 and CD22 or one tumor antigen and an IL-15 linker) antibodies or scFv have been developed." (PMID 32273348, 2020). "The frequencies of TRACCAR T cells detected at the CD22(+) tumor sites were similar in all groups regardless of IL-12P70 status, suggesting that genetic engineering does not affect the trafficking or early accumulation of T cells." (PMID 31723132, 2019). "LCEVs also carry tumor antigens and MHC I, and are loaded with tumor surface molecules, such as CD19, CD20, and CD22, which may participate in the important signaling pathways that are involved in cell-to-cell communication in LME." (PMID 30583481, 2018). "A subcategorization was possible in these diseases, dividing tumor cell expression profile of CD19 and CD22 into those cases with high expression of both markers, low levels of both markers, and of cases with high expression of one marker and low expression of the other." (PMID 29316610, 2018). "Following preliminary analysis of tumors, single cell suspensions were made and tumor cells were analyzed by flow cytometry to determine if the presence of vIL-6 influenced gene expression of common B cell markers on tumor cells (CD45, CD19, CD20, CD22, CD30, and CD138)." (PMID 30265712, 2018). "We investigated whether the soluble factors present in the medium of co-cultured CAR T and tumor cells are responsible for the down modulation of CD19, CD20 and CD22 on Raji cells in a transwell co-culture assay." (PMID 28515942, 2017). "BL is composed of monomorphic B-cells with basophilic cytoplasm and numerous mitotic figures that express B-cell antigens such as IgM, CD19, CD20, CD22, and CD79b, germinal center markers such as CD10 and BCL-6, and the proliferation marker Ki-67 in nearly all tumor cells." (PMID 27818811, 2016). "In that study, unlabelled anti-CD20 veltuzumab was administered to deplete the circulating B cells, enhancing biodistribution of the anti-CD22 radioconjugate 90Y-epratuzumab tetraxetan without interfering with tumour targeting." (PMID 25792453, 2015). "Lastly, expression of CD22, which functions as an inhibitory receptor for B-cell receptor signaling was low on ~98% of BCWM.1 tumor cells (MESF 15,665.8), lesser so on 63% of MWCL-1 cells (MESF 2,819.4) and scarcely present on 20% of RPCI-WM1 cells (MESF 958.8)." (PMID 25853860, 2015). "In B-LBL, tumour cells are virtually always positive for B cell markers CD19, CD79a and CD22." (PMID 26416427, 2015).